RNU6-154P (RNA, U6 small nuclear 154, pseudogene)
Gene: Small nuclear RNA gene on chromosome X (116,400,848 to 116,400,953, reverse strand). Ensembl gene ENSG00000207033.
Homologues: Orthologues: chimpanzee U6 (100% identical), macaque U6 (90% identical), mouse Gm23453 (90% identical), guinea pig U6 (87% identical), rabbit U6 (81% identical). Paralogues in human: RNU6-1 (93% identical), RNU6-15P (93% identical), RNU6-2 (93% identical), RNU6-25P (93% identical), RNU6-3P (93% identical), RNU6-4P (93% identical), RNU6-5P (93% identical), RNU6-6P (93% identical), RNU6-9 (93% identical), RNU6-12P (92% identical), RNU6-13P (92% identical), RNU6-16P (92% identical), and 1288 more.